TIMP2 (TIMP metallopeptidase inhibitor 2)
Diseases named in the same sentence as TIMP2 in open-access papers (continued):
Sharing a sentence is not in itself a finding about the gene and the disease.
kidney disease (11 papers, 2014 to 2024). "On the other hand, the involvement of MMP-2 and TIMP-2 in kidney disease progression has been demonstrated." (PMID 38610612, 2024). "The secretion of [IGFBP7] · [TIMP-2] in this patient might have been connected to his renal disease." (PMID 26651477, 2015). "In addition, serum TIMP-2 levels were ~5-fold higher in kidney disease compared with the healthy specimens." (PMID 24520285, 2014). "Notably, the expression of TIMP2 is significantly higher in renal biopsies with renal disease." (PMID 37489457, 2023). "Furthermore, miR-483-5p targets TIMP2 and MAPK1 in renal tubular epithelial cells, both of which are involved in the pathogenesis of renal disease." (PMID 37489457, 2023). "Prior animal studies have examined TIMP-2 in relation to AKI, and several studies have examined IGF binding proteins in renal disease but none have directly determined the performance of [TIMP-2]·[IGFBP7] for the prediction of RIFLE I/F AKI in an experimental model." (PMID 27245788, 2016).
adenocarcinoma (7 papers, 2014 to 2025). A common cancer characterized by the presence of malignant glandular cells. "After 24 h on a 3D RPM, the migration-related genes MMP-2, MMP-9, TIMP-1, and TIMP-2 were all upregulated both in a squamous (H1703) and in an adenocarcinoma (A549) cell line." (PMID 37048115, 2023). "When adenocarcinoma A549 cells were exposed to the microgravity environment, MMP-2, MMP-9, TIMP-1, and TIMP-2 showed higher expression in the MG than in the CONT at 24 h." (PMID 31601869, 2019).
cardiovascular disease (5 papers, 2010 to 2024). "It has been reported that the knockdown of TIMP2 is related to the progression of cardiovascular disease." (PMID 37891465, 2023). "TIMP-2 was studied primarily as a marker that was highly up-regulated in earlier studies with gasoline emissions and is known to have a broad involvement in cardiovascular disease." (PMID 20197249, 2010).
heart disease (5 papers, 2014 to 2022). "Cigarette smoking, a predominant factor for lung tumorigenesis, was reported to decrease TIMP-1, TIMP-2, or TIMP-3 expression in patients with heart disease or NSCLC." (PMID 33126605, 2020). "TIMP2 and TIMP3 are regulators of cardiac remodeling, hypertrophy, and fibrosis in heart disease and can be induced by Ang II." (PMID 31649814, 2019).
benign tumours (4 papers, 2015 to 2022). "In this study, we demonstrate that TIMP-2 expression in high-grade serous ovarian tumours is significantly higher than in benign tumours of the same origin." (PMID 33023532, 2020). "In the case of benign tumours, only the ovarian surface epithelium stained positive for TIMP-2." (PMID 33023532, 2020). "In benign tumours, weak expression of TIMP-2 was confined to the ovarian surface epithelium." (PMID 33023532, 2020). "Our previous studies have shown that the expression of TIMP-2 and TIMP-3 are significantly higher in high-grade serous ovarian tumours compared to benign tumours of the same origin." (PMID 36585738, 2022).
kidney (4 papers, 2017 to 2022). "The METTL3-mediated m6A modification level of TIMP2 mRNA may promote podocyte injury, apoptosis in glomeruli, and kidney inflammation through upregulating the Notch3 and Notch 4 signaling pathways." (PMID 36157472, 2022).
bacterial infection (2 papers, 2011 to 2023). "This is important because it demonstrates that microglia play a pivotal protective role in driving glial TIMP expression in two ways, first, by upregulating TIMP-2 in response to serum, and second, by facilitating astrocyte TIMP-1 expression is response to bacterial infection." (PMID 21631912, 2011).
neurodegenerative disease (2 papers, 2017 to 2024). A disorder of the central nervous system characterized by gradual and progressive loss of neural tissue and neurologic function. "Thus, elevated CSF levels of TIMPs (TIMP-1 and TIMP-2) in neurodegenerative diseases, including HD, represent a compensatory attempt at regulating already elevated and uncontrolled MMP activity." (PMID 29459817, 2017).
neurological disorders (2 papers, 2014 to 2023). "We propose that TIMP2 is a potential therapeutic agent for rescuing BBB function in neurological disorders." (PMID 38015626, 2023). "TIMP2 may be a therapeutic agent for TBI and other neurological disorders involving BBB breakdown." (PMID 38015626, 2023).
Retinopathy (2 papers, 2022 to 2023). "RANTES is a chemokine that is strongly related to retinopathy and angiopathy, and TIMP1 and TIMP2 play roles in the inhibition of EC morphogenesis." (PMID 37503820, 2023).
bone disorder (1 paper, 2023). "We found a stable profile of mRNA expression for MMP-2 and 3, TIMP-2 and -3, and a slight decline for the MMP-1 and TIMP-1 and -2 profiles during the differentiation of ASCs to osteocytes, which predispose these cells to future therapy in bone disorders." (PMID 37428795, 2023).
hereditary disease (1 paper, 2014). A disease that is caused by genetic modifications where those modifications are inherited from a parent's genome. "Nonetheless, higher TIMP-2 expression was observed in patients with hereditary disease (P=0.001)." (PMID 24527080, 2014).
TIMP2 also shares sentences with these, for which no sentence is quoted: primary open-angle glaucoma (4 papers); coronary artery disease (3); end-stage renal disease (3); intracerebral hemorrhage (3); invasive breast carcinoma (3); oral cancer (3); rhabdomyosarcoma (3); chronic periodontitis (2); Crohn disease (2); delirium (2); diabetic foot ulcers (2); Hepatic (2); Huntington disease (2); kidney cancer (2); kidney failure (2); laryngeal carcinoma (2); mesothelioma (2); Pleural effusion (2); psoriatic arthritis (2); rheumatoid arthritis (2); thoracic aortic aneurysm (2); thyrotoxicosis (2); uveal melanoma (2); acute aortic dissection (1); acute myeloid leukemia (1); alcohol (1); amyloidosis (1); Anxiety (1); Astigmatism (1); Atherosclerotic lesion (1).
A further 98 diseases each share a sentence with TIMP2 in 1 paper.